FASN (fatty acid synthase)
Diseases named in the same sentence as FASN in open-access papers (continued):
Sharing a sentence is not in itself a finding about the gene and the disease.
Insulin resistance (continued). "In this scenario, increased concentrations of serum FASN might universally occur in metabolic disorders in which insulin resistance could be prominent." (PMID 20707918, 2010). "Reduced expression of lipid metabolism genes (LPL, ACC, FASN, ACSS) in patients with insulin resistance in VAT indicates significant disturbances in lipid handling." (PMID 40806527, 2025). "In insulin-resistant (IR) children, MEG3, ATF4, FTO, ACACA, and SREBP1 were reduced, while FASN was increased." (PMID 40806129, 2025). "In adipose tissue, genes important for insulin resistance and diabetes such as PPARG and FASN were found to be KDs for TG, further supporting the connection between TG and diabetes." (PMID 33561811, 2021). "Of interest, genes related to insulin resistance, PPARG and FASN, were KDs for both the HDL and TG subnetworks." (PMID 33561811, 2021). "In the cohort presented here, liver expression levels from statin-regulated lipogenic genes such as ELOVL6, SCD and FASN, which are under transcriptional control by SREBP1, were positively correlated with insulin resistance and the diabetic status." (PMID 31159817, 2019). "The hepatic insulin resistance generated by Ccny depletion resulted in down-regulation of the sterol-regulatory element-binding protein (SREBP1) and fatty acid synthase (FASN)." (PMID 26161966, 2015). "Insulin resistance increases the expression of sterol regulatory element-binding protein (SREBP)-1c and fatty acid synthase (FasN) in the liver, elevating triglyceride (TG) accumulation." (PMID 25816097, 2015). "Additionally, liver-specific knockdown of METTL3 was shown to decrease the m6A methylation of fatty acid synthase (FASN), consequently ameliorating high-fat diet-induced insulin resistance in murine models." (PMID 41007727, 2025). "In addition, elevated levels of MGO in Drosophila have been shown to induce fatty acid synthase, hyperglycemia, MGO-adducts, and insulin resistance." (PMID 34574110, 2021). "Besides PTPN1 and STAT5A, some other genes like FASN, TAP1, which are also involved in insulin resistance, have close relationship with MCAT." (PMID 29088862, 2017). "In addition, omega-3 fatty acids through decreasing gene expression of fatty acid synthase (FAS), and phosphoenolpyruvate carboxykinase (PEPCK), reducing insulin resistance and inhibiting the inflammatory pathways triggered by cytokines can improve cardiometabolic risk." (PMID 34911587, 2021). "What’s more, FASN has a negative correlation with insulin resistance." (PMID 31788031, 2019). "Although O-GlcNAcylation of FASN in adipocytes has not been reported to date, given the fact that O-GlcNAc modification is involved in development of insulin resistance and glucose-toxicity in adipocytes, it is possible that adipocyte FASN is also regulated by O-GlcNAcylation." (PMID 30274245, 2018). "Inhibition of DNL by skeletal muscle-specific FASN deletion improves systemic insulin sensitivity without altering adiposity, but decreases muscle strength, suggesting that DNL also plays important roles in skeletal muscle, especially in states of insulin resistance." (PMID 30274245, 2018).
glioma (53 papers, 2006 to 2025). A benign or malignant brain and spinal cord tumor that arises from glial cells (astrocytes, oligodendrocytes, ependymal cells). "It was revealed that telomerase reverse transcriptase (TERT) and EZH2 jointly stimulated PCG-1α resulting in the secretion of fatty acid synthase (FASN) in glioma having (TERT) promoter mutations." (PMID 34745848, 2021). "FASN has also been linked to survival in glioma cells with activating EGFR mutations and other tumors." (PMID 22407012, 2012). "Increased expression of FASN in glioma cells is associated with increased malignancy." (PMID 35158994, 2022). "Over-expression of FASN is also associated with glioma grade." (PMID 27791206, 2016). "By supporting us, the FASN inhibitor CER was reported to decelerate 2D-colony formation in glioma and breast cancer cells." (PMID 40133683, 2025). "Another critical research study showed that FASN inhibition reduces glioma stem cells responsible for treatment resistance, migration, and invasiveness]." (PMID 40133683, 2025). "Treating human glioma cells with Cerulenin to block FASN leads to an S-phase cell cycle block and induces apoptosis, while surprisingly, the viability of normal astrocytes remains unaffected." (PMID 40097417, 2025). "FASN expression correlates with glioma grade and is found encapsulated in extracellular vesicles, potentially contributing to its dissemination in the bloodstream of glioblastoma patients." (PMID 40097417, 2025). "Increasing reports showed that inhibiting the lipogenic enzyme FASN can be a potential therapeutic target for stopping glioma progression." (PMID 40133683, 2025). "Gliomas have an accelerated de novo lipogenesis flux and often display the upregulation of FA synthase (FASN)." (PMID 40133683, 2025). "Blocking of FASN with specific shRNA or inhibitor-C75 was reported to suppress neovascularization by regulating the expression of VEGF-A in gliomas." (PMID 40133683, 2025). "The current study’s results indicated that treatments with the FASN inhibitor CER decrease the viability of glioma cells in a manner dependent on both dosage and duration." (PMID 40133683, 2025). "FASN overexpression has been described in human glioma cell lines and human glioma tissue samples, as compared to the normal human brain." (PMID 39590169, 2024). "This suggests that IDH1 MT glioma cell lines perhaps increase cholesterol biosynthesis as a compensation for FASN inhibition." (PMID 39149696, 2024). "Our analysis showed a change in FASN mRNA expression only with HDAC6 knockdown in IDH1 MT glioma cell line HK252." (PMID 39149696, 2024). "In our study, for instance, we found that only selective inhibition of FASN by TVB-2640 upregulated cholesterol metabolism in IDH1 MT gliomas." (PMID 39149696, 2024). "We further find that HDACs are involved in the regulation of lipogenic genes and HDAC6 is particularly important for the regulation of FASN in IDH1 MT glioma." (PMID 39149696, 2024). "Previous studies reported that overexpression of FASN in glioma correlated with higher WHO tumour grade and poorer prognosis." (PMID 37620304, 2023). "Later, Zhou and collaborators showed that the expression level of FASN correlated with microvessels density in human gliomas." (PMID 36934087, 2023). "FASN inhibitors induce apoptosis in glioma cells by activation of caspases 3 and downregulation of Bcl-2 protein." (PMID 38139462, 2023). "FASN is overexpressed in human glioma samples and its inhibition by Orlistat induces autophagy in glioma." (PMID 38139462, 2023). "Targeting FASN induces apoptosis and autophagy in glioma cells and decreases the expression of stemness markers in GSCs." (PMID 37620304, 2023). "At last, FASN is overexpressed in induced pluripotent stem cells, neural stem and progenitor cells and glioma stem-like cells: it is therefore likely that FASN is involved in the maintenance of stemness of CSCs." (PMID 36934087, 2023).
glioma (continued). "FASN is necessary for the expression of markers of glioma stem cells, and for the maintenance of stemness." (PMID 36934087, 2023). "Accordingly, the inhibition of FASN activity was also reported to affect CSC traits in glioma, pancreas and breast cancers." (PMID 36753044, 2023). "An increase in FASN expression has been reported as a poor prognosis, since its expression correlates with the grade of glioma." (PMID 36430793, 2022). "Inhibiting fatty acid synthase can suppress angiogenesis through modulating VEGF-A expression in glioma cells." (PMID 35902970, 2022). "In glioma harboring telomerase reverse transcriptase (TERT) promoter mutations, TERT and EZH2 cooperate with fatty acid synthase (FASN) and induce fatty acid accumulation." (PMID 34737746, 2021). "In gliomas, a key metabolic enzyme, Fatty acid synthase (FASN), that plays an important role in de novo lipogenesis, is over-expressed." (PMID 34199460, 2021). "Lastly, it has also shown tumor suppressive effects in malignant meningiomas by inhibiting fatty acid synthase (FASN), as well as stimulating apoptosis and reducing proliferation and migration in gliomas." (PMID 34199498, 2021). "These preclinical studies highlight the functional relevance of FASN for glioma growth and metabolism." (PMID 32178271, 2020). "In contrast, the increase of FASN+/CD63+ EVs in glioma patients was mainly due to augmentation of the double positive EV population as a whole." (PMID 32178271, 2020). "Inhibition of FASN with orlistat, cerulenin or C75 was found to reduce the viability and fatty acid synthesis of glioma cells and to induce autophagy and apoptosis in vitro." (PMID 32178271, 2020). "We further substantiated these findings by using IFCM and quantified FASN on circulating EVs in the blood of glioma patients, relating it to tetraspanin profiles of single EVs." (PMID 32178271, 2020). "FASN is also strongly expressed in patients with glioma stem cells (GSCs) and its inhibition reduces the expression of stem cell markers in favor of differentiation markers in GSCs." (PMID 31936544, 2020). "A study in glioma showed that the inhibition of fatty acid synthase suppresses neovascularization by regulating the expression of vascular endothelial growth factor A (VEGF-A)." (PMID 29361784, 2018). "In that study, FASN was concurrently expressed with glioma stem cell markers, including SOX2, CD133 and Nestin." (PMID 29996946, 2018). "FASN inhibitor cerulenin decreased markers of CSCs and suppressed proliferation and migration of glioma CSCs, suggesting that FASN-mediated lipogenesis plays a pivotal role in the maintenance of glioma CSCs." (PMID 30445800, 2018). "In glioma stem cells, inhibition of FASN by the fatty acid synthesis inhibitor cerulenin decreases expression of glioma stem cell markers and reduces the number of tumorspheres formed." (PMID 29996946, 2018). "FASN inhibition by cerulenin suppressed proliferation and migration as well as stemness marker expression in glioma stem cell." (PMID 28704726, 2017). "FASN was also crucial in the maintenance of glioma stem cells (GSC) stemness, and FASN-mediated de novo lipid biosynthesis was closely associated with tumor growth and invasion in glioblastoma." (PMID 28399876, 2017). "FASN expression has recently been shown to a correlate with WHO tumor grade in human glioma specimens." (PMID 26808816, 2016). "FASN overexpression has been reported in several cancers, including glioma, breast, prostate, colon, and lung cancer, compared with their respective normal tissue." (PMID 26808816, 2016). "Consequently, the present results showed that CER inhibited FASN, slowed glioma proliferation, decreased migration ability, and formed 2D and 3D colonies." (PMID 40133683, 2025). "Notably, FASN was described to be overexpressed in glioma tissue and glioma-derived extracellular vesicles." (PMID 40133683, 2025). "More recently, overexpression of FASN in gliomas has been correlated with the WHO grades." (PMID 39590169, 2024).
glioma (continued). "We conclude that targeting fatty acid metabolism through HDAC inhibition and/or FASN inhibition may be a novel therapeutic opportunity in IDH1 mutant gliomas." (PMID 39149696, 2024). "In addition, USP2 and FASN expression levels were elevated with higher tumor malignancy in gliomas, according to the WHO classification." (PMID 39489738, 2024). "USP2a acts as a DUB of FASN to stabilize the expression of FASN in glioma tissue." (PMID 37190313, 2023). "Western blotting analyses of Fatty Acid Synthase, FASN, and CD44 resulted in effective inhibition of these markers after CCT treatment, which was associated with important activation of the apoptosis program and reduced glioma cell movement and wound repair." (PMID 31936544, 2020). "Next, we analyzed FASN expression in a panel of glioma cell lines, including the glioma stem-like (GSC) cell lines BT112, BT145, NCH421k, and GS-8, which are IDH1-wildtype, the IDH1-mutated lines NCH1681, NCH551b, and BT142, and the serum-cultured glioblastoma cell line U87." (PMID 32178271, 2020). "Another question to address in future studies is whether the increase in circulating FASN+ EVs is specific for gliomas or pertains also to epithelial cancers, in which FASN is frequently overexpressed and portends a poor prognosis." (PMID 32178271, 2020). "In glioma harboring telomerase reverse transcriptase (TERT) promoter mutations, TERT and EZH2 cooperate in the activation of PGC-1α, which is involved in the expression of fatty acid synthase (FASN)." (PMID 32448308, 2020). "FASN expression has also been shown to be important in stemness preservation in glioma." (PMID 30875891, 2019). "In a glioma model, FASN expression and lipid synthesis were high in patient-derived TICs, along with glioma TIC markers SOX2, fatty acid binding protein-2 (FABP2) and nestin, and FASN inhibition led to downregulation of these markers as well as decreased viability and invasivity." (PMID 31661927, 2019). "Moreover, FASN expression was relatively higher than CPT1a in all studied glioma cells which can be in correlation to the growing cell culture characteristics and metabolic shifts towards anabolic pathways." (PMID 30574020, 2018). "This may render FASN more widely suited biomarker for identifying glioma-derived EVs than tumor-specific antigens, such as EGFRvIII or IDH1-R132, which are only expressed in distinct subtypes and, as in the case of EGFRvIII, only by a subpopulation of tumor cells within malignant gliomas." (PMID 32178271, 2020). "In general, FASN is a tumor-associated rather than a tumor-specific antigen which is overexpressed by the majority of malignant gliomas and by the majority of individual tumor cells in these gliomas." (PMID 32178271, 2020). "Future work is necessary to determine whether the increased circulating FASN+ EVs in glioma patients are truly derived from the tumor cells and whether tumor-specific genetic alteration can be detected in EVs enriched by FASN immunoprecipitation or other techniques." (PMID 32178271, 2020). "At present, it cannot be excluded that the elevated FASN+ EVs in glioma patients could also in part stem from other cell types in the tumor microenvironment, such as macrophages/microglia which possibly also exit the brain through a disrupted blood-brain barrier to enter the bloodstream." (PMID 32178271, 2020). "We therefore investigated whether FASN can serve as a novel biomarker for glioma-derived EVs." (PMID 32178271, 2020). "In our study, for the first time, the FASN inhibitor CER reduced the levels of p-PI3K (a lipid kinase family member), p-AKT, NF-κB p65 active subunit, and TNF-α in human glioma cells." (PMID 40133683, 2025). "However, the impact of FASN inhibition on the EMT of glioma cells is unknown." (PMID 40133683, 2025). "A FASN inhibitor, cerulenin (CER), reduced stemness marker expression in patient-derived glioma stem cells." (PMID 40133683, 2025).
glioma (continued). "We also found in both IDH1 MT glioma cell lines and a murine glioma model that VPA inhibited the mTOR pathway, and downregulated FASN mRNA and protein expression." (PMID 39149696, 2024). "We treated IDH1 WT cell line HK157 and 2 IDH1 MT glioma cell lines, HK252 and BT142, with VPA for four days and examined phosphorylation of ribosomal protein S6 (PS6) and FASN protein expression." (PMID 39149696, 2024). "We characterized the effect of VPA on the overall chromatin architecture of IDH1 MT gliomas and showed that VPA alters promoter accessibility and inhibits transcription of several lipogenic enzymes, including FASN, in IDH1 MT gliomas." (PMID 39149696, 2024). "We found that treatment with rapamycin also inhibited FASN mRNA and protein expression in IDH1 MT glioma cell lines." (PMID 39149696, 2024). "This further suggests that while VPA targets FASN, the net metabolic effect of VPA and TVB-2640 on the lipidome is distinct in the IDH1 MT glioma cell line and it is different when compared to the IDH1 WT cell line HK157." (PMID 39149696, 2024). "In the first study to examine the targeting of FASN in GBM, FASN enzymes were found to be expressed at a higher level in glioma tissue than in normal neuronal tissue in both humans and rats." (PMID 36594473, 2023). "This goes against the findings of several groups, in which FASN was overexpressed in GBM and was correlated with increased glioma grade." (PMID 37509679, 2023). "The therapy using some natural and synthetic anti-glioma agents, such as medicinal cannabis or cannabinoids, bipolaris setariae fungi, oncolytic viruses, neurostatin, and fatty acid synthase (FAS) inhibitors, can also help combat gliomas." (PMID 36091753, 2022). "Alterations of the mitochondrial networks are directly or indirectly involved in processes resulting in hypoxia-tolerant and hypoxia-sensitive gliomas, and by the hypoxia-inducible factor-1 (HIF-1), glycolytic protein isoforms, and fatty acid synthase." (PMID 34638954, 2021). "A previous study showed that inhibition of fatty acid synthase (FASN) blocks HIF-1α/VEGF-A signaling in response to hypoxia, and suppresses neovascularization in glioma by upregulating VEGF165b37." (PMID 33446752, 2021). "In a previous study, we analyzed EVs derived from glioma stem-like cell (GSC) lines by mass spectrometry and discovered that fatty acid synthase (FASN) was present at high levels in EVs secreted from mesenchymal as well as proneural glioblastoma cell lines." (PMID 32178271, 2020). "Mutated IDH1/2 catalyzes the synthesis of D2-HG from α-ketoglutarate, consuming NADPH that will not be available for fatty acid synthesis by fatty-acid synthase (FASN), a marker for poor prognosis in IDH-wild type gliomas." (PMID 32993063, 2020). "In accordance, fatty acid synthase (FASN), key lipogenic enzyme, can attenuate stemness in glioma cells, while their differentiation abolishes FASN expression." (PMID 28848547, 2017). "For the first time, this study revealed that Hsp70 and p-HSF1 (heat shock transcription factor 1) levels increased in glioma cells due to CER-mediated FASN inhibition, while no significant change was observed in Hsp60 and Hsp90 levels." (PMID 40133683, 2025). "Our lipidomic study suggested that although VPA targets FASN in IDH1 MT glioma cell lines, it does not deplete palmitate." (PMID 39149696, 2024). "Hence, it is possible that in order to overcome the metabolic flexibility of cancer cells, dual targeting of FASN by both VPA and TVB-2640 is potentially an effective therapeutic approach for IDH1 MT glioma." (PMID 39149696, 2024). "Together, we conclude that in IDH1 MT glioma cell lines, VPA may work through FASN to inhibit cell cycle and anti-apoptotic genes." (PMID 39149696, 2024).